RNA5SP443 (RNA, 5S ribosomal pseudogene 443)
Synonyms: RN5S443
Gene: Ribosomal RNA gene on chromosome 17 (45,327,366 to 45,327,497, reverse strand). Ensembl gene ENSG00000199953.
Homologues: Orthologues: chimpanzee 5S_rRNA (100% identical), guinea pig 5S_rRNA (66% identical). Paralogues in human: RNA5S1 (62% identical), RNA5S10 (62% identical), RNA5S11 (62% identical), RNA5S12 (62% identical), RNA5S13 (62% identical), RNA5S14 (62% identical), RNA5S15 (62% identical), RNA5S16 (62% identical), RNA5S17 (62% identical), RNA5S2 (62% identical), RNA5S3 (62% identical), RNA5S4 (62% identical), and 26 more.